STAT3 (signal transducer and activator of transcription 3)
Diseases named in the same sentence as STAT3 in open-access papers (continued):
Sharing a sentence is not in itself a finding about the gene and the disease.
mastitis (13 papers, 2013 to 2025). Inflammation of breast tissue during lactation or postpartum due to an obstructed duct or infection. "Similarly, the signal transduction and activator of transcription 3 (STAT3) and the nuclear factor-κB (NFκB) signaling pathways have been implicated in mastitis, and were also found to be crucial signaling pathways in the pathogenesis of pSS." (PMID 34277672, 2021). "The EV-miR-221/SOCS1/STAT1/STAT3 axis not only increases the proportion of M1-like macrophages in the early stage of mastitis but also provides a new direction for exploring the pathogenesis of mastitis." (PMID 35769456, 2022). "Both STAT3 and NFκB have been shown to regulate the expression of genes involved in inflammation within the mammary glands in mastitis." (PMID 24308795, 2013). "In both S. aureus-positive and S. chromogenes-positive cows, the DE snoRNAs were correlated with several immune and inflammatory genes (e.g., IL1R, IL18R1, STAT3, NFKB2, MYD88, VEGFA and CD40), all of which have been reported in several studies to be associated to mastitis." (PMID 40936092, 2025). "Whether the activation of Stat3 in myoepithelium, triggered by Il6 and interferon, in mothers with mastitis, is the etiology of lactation failure via cross-cell signal transduction requires further investigation." (PMID 37833248, 2023). "Therefore, it is suggested that the rapid shutdown of galactopoiesis is induced through the binding of LPS to AEC and the activation of STAT3 and NFkB immediately after infection in mastitis." (PMID 24308795, 2013). "Moreover, STAT3 has recently been reported as a potential therapeutic target in mastitis." (PMID 32754201, 2020). "Utilizing the PPI network, the topological parameters of Betweenness unDir, Closeness unDir, and Degree unDir were employed to predict the core targets for mint in treating mastitis in dairy cows, which include TNF, IL–6, STAT–3, IL–1β, FGF–2, IFNG, and ESR–1." (PMID 40005889, 2025). "Many of the genes within this category have previously been identified as being involved in the immune response to mastitis, including LBP, STAT3, S100A8 and SOD2." (PMID 23324411, 2013). "It has been proposed that sinomenine hydrochloride may have therapeutic effects on plasma cell mastitis based on its anti–inflammatory and immunomodulatory properties, which are exerted through the downregulation of the IL–6/JAK2/STAT–3 pathway." (PMID 40005889, 2025). "Although some studies have shown that the IL-6/JAK2/STAT3 signaling pathway is related to non-puerperal mastitis, such reports are few." (PMID 37817809, 2023).
metabolic syndrome (13 papers, 2015 to 2025). A cluster of metabolic risk factors for CARDIOVASCULAR DISEASES and TYPE 2 DIABETES MELLITUS. "This provides evidence that STAT3 can transcriptionally repress lipid metabolism in the liver and that repressive control of hepatic adaptive metabolism is conserved across metabolic syndromes." (PMID 38632714, 2024). "In contrast, another study demonstrated that metabolic syndrome mimicked by high glucose, salt, and cholesterol treatment in cardiomyocyte-like H9c2 cells reduced viability and STAT3 activation." (PMID 30424579, 2018). "Moreover, increased STAT3 expression has been shown to contribute to the development of left ventricular hypertrophy in hypercholesterolemic hamsters and pigs suffering from metabolic syndrome." (PMID 30424579, 2018). "We obtained overlapping genes between Danshen compounds and dyslipidemia, and through a PPI network analysis, key target genes such as JAK2, STAT3, PI3K, AKT1, and TLR4 were acquired." (PMID 39598338, 2024). "Similar to IFNG, the expressions of JAK1 and STAT3 were statistically lower in subjects with dyslipidemia (G1, G2, and G3), and significant negative correlations were found between these genes and lipid parameters." (PMID 28316372, 2017). "Patients with dyslipidemia demonstrated statistically higher expression of the IL10 and IFNA genes, while IFNG, IP10, IRF1, JAK1, and STAT3 were lower in comparison with nondyslipidemic patients." (PMID 28316372, 2017).
nonalcoholic steatohepatitis (13 papers, 2017 to 2025). "In palmitic-acid-treated macrophages, the amount of pSTAT3 decreased after treatment with liraglutide, suggesting that STAT3-mediated proinflammatory signaling in macrophages is critical in nonalcoholic steatohepatitis livers." (PMID 35052861, 2022). "An FXR activator blocked nonalcoholic steatohepatitis-dependent HCC progression by suppressing the SOCS3/Jak2/STAT3 pathway." (PMID 35999582, 2022). "STAT1 and STAT2 have been shown to inhibit HCV replication after being activated by IFNs, while activation of STAT1 and STAT3 are found in non-alcoholic steatohepatitis (NASH)." (PMID 35871161, 2022). "PTGS2 (degree = 14) amplifies inflammatory cascades by converting FASN-derived arachidonic acid into protumorigenic prostaglandin E2, establishing a self-perpetuating lipid-inflammation feedforward loop that drives IL-6/STAT3-mediated malignant transformation in non-alcoholic steatohepatitis." (PMID 40839202, 2025). "In nonalcoholic steatohepatitis (NASH)-derived HCC, androgen receptor (AR)-driven oncogene cell-cycle-related kinase (CCRK) induces the STAT3–AR axis, activates the mTORC1 cascade, and enhances MDSC recruitment and tumorigenicity." (PMID 40722703, 2025).
preeclampsia (13 papers, 2014 to 2025). Preeclampsia is a hypertensive disorder of pregnancy that is characterized by new-onset hypertension with proteinuria presenting after 20 weeks of gestation, and depending on mild or severe forms may initially present with severe headache, visual disturbances, and hyperreflexia. "Both ATF2 and STAT3 are associated with preeclampsia; studies indicate that elevated levels of ATF2 characterize preeclamptic women, normalizing after low-dose aspirin interventions." (PMID 39596234, 2024). "Low levels of EGF and reduced STAT3 phosphorylation are implicated in preeclampsia and IUGR." (PMID 28542650, 2017). "It has been reported that the expression of ribosomal protein S4 is elevated in placental tissues of patients with preeclampsia, while the phosphorylation level of STAT3 in serum is decreased." (PMID 38235138, 2023). "In preeclampsia placenta tissues, the change of STAT3 expression is related to the altered migration and the invasion of the trophoblast." (PMID 37038114, 2023). "Recent studies show that FKBPL regulates inflammatory STAT3 signalling, via CD44 and NFkB, which are both implicated in preeclampsia." (PMID 33879252, 2021). "Additionally, the detrimental effects of the over-activation of the JAK2/STAT3 pathway have been observed in placentas obtained from animal models of preeclampsia, such as rats stimulated with L-NAME." (PMID 39596234, 2024). "The IL-6/STAT3 signaling pathway could be repressed by pravastatin to alleviate oxidative stress, improve preeclampsia, and decrease the apoptosis of placental trophoblastic cells in rats with PE39." (PMID 37828060, 2023). "In summary, the suppression of the STAT3 signaling pathway in trophoblast cells may lead to cell apoptosis and impaired cell migration, thus facilitating the onset of preeclampsia." (PMID 38235138, 2023). "Mechanistically, RORA activates the JAK2/STAT3 signaling pathway to exacerbate preeclampsia." (PMID 38235138, 2023). "Furthermore, it has been found that miR-125b is up-regulated in the serum of preeclampsia patients, which inhibits the STAT3 pathway and suppresses the migration and invasion of extravillous trophoblast cells." (PMID 38235138, 2023). "Several studies have revealed that the STAT3 may be involved in the pathophysiologic processes of preeclampsia." (PMID 34645519, 2021). "It is also reported that STAT3 and its phosphorylated form are significantly decreased in EVT, villous trophoblast and entire placentas in patients with preeclampsia." (PMID 28542650, 2017). "Conversely, other studies utilizing trophoblastic cell lines emphasize that the strongest activation of STAT1, JAK1/STAT3, and STAT5 pathways in preeclampsia is a compensatory mechanism; these pathways enhance trophoblast proliferation and invasion while exacerbating apoptosis." (PMID 39596234, 2024). "The JAK/STAT3 pathway works closely with leukemia inhibitory factor (LIF) to induce inflammation and endothelial dysfunction, characterized by increased levels of intercellular adhesion molecule-1 (ICAM-1) and vascular cell adhesion molecule-1 (VCAM-1), all of which are hallmarks of preeclampsia." (PMID 39596234, 2024). "Additionally, it has been discovered that down-regulation of Annexin7 in placenta of preeclampsia patients inhibits the JAK1/STAT3 pathway in trophoblast cells, leading to a decrease in BCL2 protein levels and induction of cell apoptosis, thus contributing to the development of preeclampsia." (PMID 38235138, 2023).
uveitis (13 papers, 2012 to 2025). An inflammatory process affecting a part of or the entire uvea. "Stat3 activates miR-155 and the Stat3/miR-155 axis mediate severe uveitis by promoting the expansion of pathogenic Th17 cells." (PMID 33995347, 2021). "Taken together, STAT3 exerts diametrically opposite effects in lymphocytes, with loss of STAT3 in B cells exacerbating uveitis whereas Stat3 deletion in T cells confers protection." (PMID 33004854, 2020). "In this study, we investigated whether loss of STAT3 in mature B cells would promote resistance or susceptibility to uveitis and to evaluate the safety and efficacy of targeting STAT3 pathways as immunotherapy for this potentially blinding disease." (PMID 33004854, 2020). "We further show that ORLL-NIH001 blocked the transcriptional activity of STAT3 and antagonized the expansion of human Th17 cells, providing suggestive evidence that it can be used to treat uveitis and other chronic inflammatory diseases caused by Th17 and Th17-DP cells." (PMID 22238646, 2012). "Interestingly, the decrease in Treg and Breg subsets and marked increase in Th17 signature cytokines during EAU and EAE in CD19-STAT3KO mice may provide a mechanistic link between loss of STAT3 pathways in B cells and development of severe uveitis." (PMID 33004854, 2020). "Taken together, these findings establish that the main target of SBT-100 is the SH2 domain and this is consistent with our published report that SBT-100 inhibits the STAT3 pathway of uveitogenic Th17 and Th1 cells that mediate uveitis." (PMID 38920670, 2024). "Inflammatory cytokines have also been shown to induce expression of miR-155 in human RPE cells, further suggesting that Stat3 is a potential therapeutic target for treating uveitis." (PMID 33995347, 2021). "Targeting STAT3 pathway that is required for the differentiation and expansion of Th17 cells has been proposed as a potential therapy for mitigating uveitis because genetically modified mice that cannot induce Th17 cells are resistant to developing uveitis." (PMID 34603297, 2021). "Taken together, analysis of mouse uveitis model and the blood of human uveitis patients identified roles of Th17 cells and STAT3 pathway in uveitis and that STAT3 pathway is a potential target for treatment of uveitis." (PMID 33995347, 2021). "CD4-STAT3KO mice do not develop EAU because of defect in generating Th17 cells, suggesting that STAT3 is a potential therapeutic target for modulating uveitis." (PMID 33995347, 2021). "In contrast to mild uveitis observed in WT mice, mice with conditional deletion of STAT3 in the B cell compartment developed severe EAU characterized by massive infiltration of inflammatory cells into the retina and targeted destruction of photoreceptor cells." (PMID 33004854, 2020). "Consistent with the role of Th17 in etiology of uveitis, mice with targeted deletion of STAT3 in the CD4+ T cell compartment (CD4-STAT3KO) are resistant to development of EAU." (PMID 22238646, 2012). "In this study, we have shown that ORLL-NIH001, a small molecule that targets STAT3 pathways in T cells was effective in mitigating uveitis in mice." (PMID 22238646, 2012). "The transcription factor STAT3 is implicated in uveitis because mice with loss of STAT3 in CD4+ T cells do not develop EAU." (PMID 40114923, 2025). "The Th1 and Th17 cell subsets require STAT1 and STAT3 during development and may be the etiological agents responsible for human uveitis and scleritis and experimental autoimmune uveoretinitis." (PMID 34966823, 2021). "In this study, we generated mice with targeted deletion of STAT3 in B cells and investigated intrinsic and extrinsic functions of STAT3 in B cell, with particular focus on the role of STAT3 in uveitis, the mouse model of human uveitis." (PMID 33004854, 2020). "Specifically, we examined whether the loss of STAT3 affected the development of the CD8+ T cell phenotype or its regulatory functions during HSV-1 infection and mouse uveitis." (PMID 24204098, 2013).
uveitis (continued). "Thus, the recent success in ameliorating uveitis by use of small chemical inhibitors of STAT3 cannot be wholly attributed to inhibition of Th17 cells." (PMID 24204098, 2013). "In this study, we examined whether ORLL-NIH001, an inhibitor of STAT3, would be efficacious in mitigating uveitis." (PMID 22238646, 2012). "Requirement of STAT3 for generation of Th17 and Th17-DP cells also suggest that the STAT3 pathway is a potential therapeutic target that may be used to prevent or mitigate uveitis." (PMID 22238646, 2012). "These double expressors are absent in CD4-STAT3KO mice, indicating that they are also regulated by STAT3 and raising the intriguing possibility that uveitis maybe mediated not only by Th17 but also by Th17-DP cells." (PMID 22238646, 2012). "To investigate the impact of deleting STAT3 in CD19+ B cells on the development and severity of uveitis, we induced EAU in WT control and CD19-STAT3KO mice by active immunization with the uveitogenic peptide, IRBP651-670 in CFA emulsion." (PMID 33004854, 2020). "As induced rodent models of uveitis have shown that either Th1 or Th17 T lymphocytes can promote experimental uveitis, the ability of SOCS1-KIR to regulate both STAT1 and STAT3 signaling may be particularly valuable in inhibiting uveitogenic effector functions." (PMID 35505065, 2022). "Thus, increases of IL-6-induced STAT3 activation observed during inflammation may inhibit expansion of CD8-Tregs, thereby impeding recovery from uveitis." (PMID 24204098, 2013). "Taken together, these results suggest that STAT3 signaling is required for recruitment of T cells into retina and development of EAU and that drugs that block STAT3 signal transduction pathway may be useful in mitigating uveitis." (PMID 22238646, 2012).
abdominal aortic aneurysm (12 papers, 2020 to 2025). Enlargement and ballooning of the vessel that supplies arterial blood to the abdomen, pelvis and legs. "Meanwhile, lncRNA SNHG16 upregulates the expression of STAT3 by inhibiting the binding of miR-106b-5p to STAT3, ultimately forming a complex deteriorating loop in abdominal aortic aneurysm (AAA) by regulating VSMCs." (PMID 38172648, 2024). "Additionally, miR-4688 targeting TULP3 promotes the formation of abdominal aortic aneurysms through the STAT3/NEAT1/miR-4688/TULP3 axis." (PMID 40282234, 2025). "A study of human arterial tissue also showed that blocking JAK2/STAT3 pathway could attenuate the progress of abdominal aortic aneurysm." (PMID 37089432, 2023). "Moreover, STAT3 may function as one positive feedback regulator that induces the upregulation of NEAT1 as a competing endogenous RNAs (ceRNA) that then facilitates abdominal aortic aneurysm formation by targeting the miR-4688/TULP3 axis." (PMID 33546665, 2021).
aneurysm (12 papers, 2011 to 2025). Bulging or ballooning in an area of an artery secondary to arterial wall weakening. "Furthermore, vascular abnormalities and increased aneurysm risk have been identified in patients with missense STAT3 variants causally implicating this pathway in vascular regulation." (PMID 39215134, 2024). "Frequent cerebral and coronary artery ectasias and aneurysms were observed in patients with STAT3 deficiency, suggesting JAK/STAT-dependent signaling may be implicated in the maintenance of vessel integrity." (PMID 24586754, 2014). "IL1-7A, which is mediated by the activation of STAT3, induces aneurysm development by the production of pro-inflammatory cytokines in macrophages through the MAP kinase, NF-κB, and AP-1 pathways, thereby influencing macrophages and activating atherogenesis." (PMID 39737187, 2024). "A relevant study showed that overexpression of SOCS3 in bone marrow-derived cells significantly increased aneurysm severity (P = 0.04) demonstrating that STAT3/SOCS3 signaling in bone marrow-derived cells contributes to AAA development." (PMID 33415145, 2020). "Moreover, as the downstream targets of JAK2, phosphorylation of signal transducer and activator of transcription 3 and 1 (p-STAT1 and p-STAT3) were also significantly higher in fusiform aneurysms compared with the normal cerebral arteries." (PMID 38741091, 2024). "Also, the STAT3 inhibitor, BP-1-102, can reduce the expression of inflammatory factors and MMPs bound to NF-kB by inhibiting the activation of the JAK/STAT3/NF-kB pathway, and then restore the vascular wall elastin to reduce blood pressure, thereby treating aneurysms in mice." (PMID 38137108, 2023). "CircHipk3 serves a dual role in augmenting macrophage pyroptosis by interaction with Stat3, increase the NLRP3 level, and by binding Snd1 to promote Ptbp1 mRNA degradation to inhibit autophagy, thereby inducing aneurysm formation and progression." (PMID 39601144, 2024). "Tortuosity and ectasia appear to develop with increasing age and may be explained by STAT3-mediated transcription of VEGF and hypoxia-inducible factor (HIF)-1α, whose expression are reduced in STAT3-HIES, and through dysregulated MMPs: MMP-8 is specifically implicated in aneurysm formation." (PMID 33932191, 2021).
autoimmune myocarditis (12 papers, 2013 to 2025). Autoimmune myocarditis is an autoimmune disease that affects the heart. "PPARα inhibits activator protein −1 (AP-1)-dependent genes involved in inflammation and tumor progression and suppresses Th17 cells through modulation of IL-6/STAT3/RORγt signaling in rat models of autoimmune myocarditis." (PMID 38398835, 2024). "It has been reported berberine from C. chinensis notably attenuates the excessive expression of p-STAT3 in the rats with autoimmune myocarditis." (PMID 29318137, 2017). "Comparable results showed that EMPA could abate the expression of STAT3 in various scenarios, including lipopolysaccharide-induced inflammation and autoimmune myocarditis." (PMID 40143181, 2025). "A recently study on autoimmune myocarditis reported PPARα may play an important role by regulating IL-6/STAT3 pathway on Th17 cell differentiation which contributes to inflammatory response." (PMID 35414769, 2022). "In conclusion, Bazedoxifene affected STAT3 signaling and prevented cardiac inflammation deterioration, so may provide a promising therapeutic strategy for the treatment of experimental autoimmune myocarditis (EAM)." (PMID 33643041, 2020).